MPV17 (mitochondrial inner membrane protein MPV17)
Description:
Non-selective channel that modulates the membrane potential under normal conditions and oxidative stress, and is involved in mitochondrial homeostasis. Involved in mitochondrial deoxynucleoside triphosphates (dNTP) pool homeostasis and mitochondrial DNA (mtDNA) maintenance. May be involved in the regulation of reactive oxygen species metabolism and the control of oxidative phosphorylation (By similarity).
Synonyms: SYM1; CMT2EE; MTDPS6
Tractability: Antibody: UniProt predicts a signal peptide or a membrane-spanning region. PROTAC: ubiquitination databases record sites on it; its protein half-life has been measured.
Gene: Protein-coding gene on chromosome 2 (27,309,486 to 27,325,680, reverse strand). Ensembl gene ENSG00000115204.
Subcellular location: Mitochondrion inner membrane
Pathways (Reactome):
Protein localization: Peroxisomal protein import
Gene Ontology:
Molecular function: channel activity
Biological process: glomerular basement membrane development; inner ear development; transmembrane transport
Cellular component: mitochondrial inner membrane; mitochondrion; peroxisome; cytosol; peroxisomal membrane; membrane
Genetic constraint (gnomAD): Loss-of-function variants: 29 observed, 28.9 expected, observed/expected ratio (o/e) 1, 90% interval 0.75 to 1.37. The upper end of that interval is the gene's LOEUF score, 1.37, which puts it in group 5 of 6, group 1 being the genes least tolerant of losing a copy. Missense variants: 197 observed, 227.02 expected, observed/expected ratio (o/e) 0.87, 90% interval 0.77 to 0.98. Synonymous variants: 87 observed, 90.14 expected, observed/expected ratio (o/e) 0.97, 90% interval 0.81 to 1.15.
Gene-disease validity (ClinGen):
ClinGen rates the evidence that MPV17 causes each of these diseases.
mitochondrial disease (autosomal recessive): Definitive.
Homologues: Orthologues: chimpanzee MPV17 (99% identical), macaque MPV17 (98% identical), dog MPV17 (92% identical), mouse Mpv17 (92% identical), guinea pig MPV17 (90% identical), pig MPV17 (87% identical), rabbit MPV17 (78% identical), rat Mpv17 (71% identical), zebrafish mpv17 (69% identical), tropical clawed frog mpv17 (59% identical), Drosophila melanogaster Mpv17 (35% identical), Caenorhabditis elegans T18D3.9 (32% identical). Paralogues in human: PXMP2 (32% identical), MPV17L2 (31% identical), MPV17L (27% identical).
Diseases named in the same sentence as MPV17 in open-access papers:
MPV17 is named in the same sentence as 69 diseases in open-access papers, as found by Europe PMC text mining. Sharing a sentence is not in itself a finding about the gene and the disease. The quoted sentences say what the papers report.
mitochondrial DNA depletion syndrome (12 papers, 2013 to 2025). The mitochondrial DNA (mtDNA) depletion syndrome (MDS) is a clinically heterogeneous group of mitochondrial disorders characterized by a reduction of the mtDNA copy number in affected tissues without mutations or rearrangements in the mtDNA. "Yeast Saccharomyces cerevisiae SYM1 is an ortholog of human MPV17, whose mutations cause mitochondrial DNA depletion syndrome (MDDS)." (PMID 36899826, 2023). "In the humans, many mutations of this gene had been reported, and the mpv17 mutation was associated with mitochondrial DNA depletion syndrome and caused death during early childhood." (PMID 34537814, 2021). "Recessive mutations in the MPV17 gene cause mitochondrial DNA depletion syndrome, a fatal infantile genetic liver disease in humans." (PMID 26921094, 2016). "In humans, severe MPV17 deficiency has been associated with a hepatocerebral form of mitochondrial DNA depletion syndrome which results in death due to liver failure at young ages, while less severe mutations have been linked to juvenile-onset peripheral neuropathy." (PMID 34413725, 2021). "Likewise, several mutations in mpv17 were reported to be associated with mitochondrial DNA depletion syndrome in humans causing death during early childhood." (PMID 23862018, 2013). "Interestingly, in humans the loss-of-function of GUOK, a mitochondrial matrix enzyme involved in guanosine nucleotide salvage pathway, also causes mitochondrial DNA depletion syndrome with a comparable phenotypic outcome to mpv17 mutations." (PMID 23862018, 2013). "Eight patients with MPV17-related mitochondrial DNA depletion syndrome who had undergone brain MRI were identified between 2015 and 2023." (PMID 40773069, 2025). "MPV17 is a mitochondrial inner membrane protein whose loss of function impairs oxidative phosphorylation and results in severe mtDNA depletion syndrome in humans and in MPV17−/− mice." (PMID 30427907, 2018). "Iridophore death might be the result of mitochondrial dysfunction, consistent with the mitochondrial DNA depletion syndrome observed in mammalian mpv17 mutants." (PMID 23862018, 2013).
liver failure (7 papers, 2014 to 2025). A liver disease characterized by the liver losing or has lost all of its function. "Differential diagnosis should also be considered with other mitochondrial disorders causing liver failure (MPV17, POLG1, POLG2, TFAM, TWNK, TRMU)." (PMID 38756539, 2024). "Hepatocerebral variant related to MPV17 gene defect is characterized by infantile onset of progressive liver failure, developmental delay, neurological manifestations, lactic acidosis, hypoglycemia, and mtDNA depletion in liver tissue." (PMID 37384111, 2023). "The infantile phenotypes of hepatocerebral forms of MDS associated with mutations in POLG, PEO1 (Twinkle), DGUOK or MPV17 have similarities, presenting with liver failure along with various neurological and endocrinological manifestations." (PMID 23714749, 2014). "Sequencing of the DGUOK, POLG and MPV17 genes did not reveal the causative mutation, however, it is possible that the mtDNA depletion contributed to the liver failure in these patients." (PMID 27053192, 2016).
mitochondrial DNA depletion syndrome 6 (6 papers, 2015 to 2025). "MPV17 mutations classically cause mitochondrial DNA depletion syndrome 6 (Navajo neurohepatopathy) with infantile, childhood, and classic phenotypes encompassing hepatic dysfunction and neuropathy." (PMID 40869966, 2025). "To date, 56 mutations have been reported in MPV17, the majority of which cause a condition called mitochondrial DNA depletion syndrome-6 (MTDPS6: 256810)." (PMID 36833258, 2023). "MPV17 - a homozygous variant in exon 4 (c.210>A) causing mitochondrial DNA depletion syndrome 6 (hepato-cerebral type), an autosomal recessive disorder." (PMID 37519562, 2023). "Mutations in MPV17 cause the autosomal recessive disorder mitochondrial DNA depletion syndrome 6 (MTDPS6), also called Navajo neurohepatopathy (NNH)." (PMID 26437932, 2015). "Mutations in MPV17 cause mitochondrial DNA depletion syndrome 6 (MTDPS6) (NNH; MIM #256810), also known as Navajo neurohepatopathy, an autosomal, recessive, multi-system disorder." (PMID 26437932, 2015). "Biallelic homozygous MPV17 variants have been reported to result in juvenile-onset isolated peripheral sensorimotor neuropathy (CMT2EE) without hepatocerebral involvement, as occurs in autosomal recessive (AR) mitochondrial DNA depletion syndrome 6 (Navajo neurohepatopathy)." (PMID 37712079, 2023).
glomerulosclerosis (4 papers, 2013 to 2021). A hardening of the kidney glomerulus caused by scarring of the blood vessels. "MPV17 gene knockout in mice has been described earlier as causal of glomerulosclerosis and inner ear disease, reminiscent of chemical damage by Adriamycin." (PMID 26921094, 2016). "The mpv17 mutant mice developed mitochondrial DNA depletion, late-onset glomerulosclerosis, hair graying, and the neurodegeneration of the peripheral nervous system." (PMID 34537814, 2021). "Subsequently, more works were reported on the mouse Mpv17 defect, implying that the function of the Mpv17 gene was involved in the ROS production and glomerulosclerosis." (PMID 34537814, 2021). "Whereas the Mpv17 KO mouse strain mainly shows glomerulosclerosis and inner ear defects (Löllgen and Weiher, 2014), the zebrafish mpv17 null mutant phenotype is mostly characterized by a specific lack of iridophores and a progressive loss of melanophores, both derived from the neural crest." (PMID 30833296, 2019).
liver disease (4 papers, 2015 to 2023). "While MPV17-deficient humans developed liver disease, Mpv17-deficient mice suffered from renal failure." (PMID 36899826, 2023). "MPV17 deficiencies in humans can cause fatal liver disease mediated by mitochondrial DNA depletion in liver cells." (PMID 26921094, 2016). "This contrasts with the experience in ALF due to hepatocerebral MDS from bi-allelic mutations in POLG, DGUOK or MPV17 commonly manifesting as multi-system disorders before or shortly after onset of liver disease." (PMID 27483465, 2016). "Several MPV17 mutations have been reported in association with a heterogeneous group of early-onset manifestations, including liver disease and neurological problems." (PMID 26353863, 2015).
neuropathy (4 papers, 2012 to 2025). A disorder affecting the nervous system that manifests with pain, tingling, numbness, and/or muscle weakness. "The identification of pathogenic variants in well-established neuropathy-associated genes such as PMP22, MME, MPV17, and HINT1 confirms the value of CES, particularly when traditional single-gene screening is inconclusive." (PMID 41509941, 2025).
acute liver failure (2 papers, 2016 to 2025). Rapid deterioration of liver function causing encephalopathy and coagulopathy. "Another study performed whole exome sequencing in three children with acute liver failure and identified pathogenic mutations in MPV17, SERAC1 and NOTCH2, despite the lack of characteristic clinical phenotypes for these genes." (PMID 27053192, 2016).
hepatocellular carcinoma (2 papers, 2011 to 2015). A malignant tumor that arises from hepatocytes. "Since then other reports also support a role for MPV17 and deoxyguanosine kinase SUCLA2 mutation induced hepatocellular carcinoma in MDS patients." (PMID 26468652, 2015). "However, our recent study revealed that infant patients with mutations in DGUOK (deoxyguanosine kinase) MPV17 genes had developed hepatocellular carcinoma (HCC)." (PMID 22028711, 2011).
iron overload (2 papers, 2024 to 2025). "The decreased expression levels of Nrf2 led to the inactivation of MPV17 in iron overload-induced myocardial ferroptosis." (PMID 39409161, 2024).
acute-on-chronic liver failure (1 paper, 2024). Acute-on-chronic liver failure (ACLF) is an extreme condition during the natural history of chronic HBV infection, with a relatively high short-term mortality.
cardiac ischemia (1 paper, 2024). "Moreover, we found an emerging role of MPV17 in protecting cardiomyocytes from iron overload-induced ferroptosis and attenuating cardiac ischemia/reperfusion (I/R) injury through maintaining the protein homeostasis of SLC25A10, which imports GSH from the cytosol into the mitochondria." (PMID 39409161, 2024).
cardiomyopathy (1 paper, 2023). A disease of the heart muscle or myocardium proper. "Twelve of the 52 mouse models identified with cardiomyopathy (Acadv1, Fxn, Mto1, Taco1, Hmgcs2, Mpv17, Opa1, Pnpla8, Tmem126b, Gpd2, Mpv17, Micu1) showed that the presence of cardiomyopathy can be dependent on the degree of stress." (PMID 37103033, 2023).
Charcot-Marie-Tooth (CMT) disease (1 paper, 2022). "Autosomal recessive mutations in the MPV17 gene have also been identified in patients with Charcot-Marie-Tooth (CMT) disease, the most common inherited motor and sensory peripheral neuropathy." (PMID 36587049, 2022).
cognitive defects (1 paper, 2022). "In conclusion, we first showed that CG11077 is an ortholog of mammalian Mpv17 and that neuron-specific CG11077 knockdown induced both locomotor and cognitive defects in Drosophila larvae, depending on the mitochondrial dysfunction involved." (PMID 36587049, 2022).
congenital heart disease (1 paper, 2025). A heart disease that is present at birth. "Notably, the MPV17 variant in our patient coincided with congenital heart disease, representing the first such association in the literature." (PMID 40869966, 2025). "Notably, a previously unreported co-occurrence of MPV17 mutation and congenital heart disease was observed in one case." (PMID 40869966, 2025).
coronary artery disease (1 paper, 2025). "This study identified MPV17 as a key mitochondrial gene bridging peripheral artery disease (PAD) and coronary artery disease (CAD)." (PMID 40708652, 2025).
demyelinating peripheral neuropathy (1 paper, 2019). "This phenotype perfectly matches the Mpv17−/− mouse premature greying and the progressive demyelinating peripheral neuropathy found in 38% of MPV17 mutant patients, features that we can consider possible neurocristopathies." (PMID 30833296, 2019).
diabetes (1 paper, 2023). "Mpv17 deficiency also attenuated Ins2Akita-induced β-cell loss and diabetes, suggesting that MPV17 promotes ER stress-induced β-cell injury." (PMID 37522959, 2023). "Mpv17 deficiency was also found to confer resistance to the diabetes induced by an insulin mutation (Ins2Akita), which represents a mouse model of monogenic diabetes characterized by proinsulin misfolding and β-cell failure." (PMID 37522959, 2023). "Mpv17 knockout mice were resistant to not only STZ-induced diabetes but also proinsulin mutation (Ins2Akita) induced diabetes." (PMID 37522959, 2023). "We found that the Mpv17 mutant mice were also resistant to the diabetes induced by insulin 2 mutation (Ins2Akita)." (PMID 37522959, 2023). "In the present study, we show that MPV17 is expressed in β cells and that Mpv17 deficiency confers resistance to apoptosis in the two mouse models of diabetes, STZ and Ins2Akita, indicating that MPV17 acts in β-cells to promote apoptosis and facilitate the development of diabetes." (PMID 37522959, 2023). "To prove that MPV17 deficiency-conferred resistance to diabetes is β-cell autonomous, we examined whether MPV17 is expressed in β-cells." (PMID 37522959, 2023). "In addition, β-cell and podocyte specific knockout of Mpv17 would provide tools to address the opposite effects of MPV17 in the two cell types, providing insights into the mechanisms underlying not only diabetes but also diabetic kidney disease." (PMID 37522959, 2023). "It would be interesting to investigate the role of MPV17 in β-cell dedifferentiation and dysfunction in various types of diabetes." (PMID 37522959, 2023). "In fact, determining the role of MPV17 in podocyte injury in diabetes was our original aim of study." (PMID 37522959, 2023). "In both diabetes models, Mpv17 knockout mice exhibited lower levels of blood glucose, β-cell loss, and apoptosis." (PMID 37522959, 2023). "Identification of MPV17 as a novel regulator of β-cell death has provided a potential target for treatment of Type 1 diabetes and some monogenic forms of diabetes." (PMID 37522959, 2023). "To test whether MPV17 is also protective in diabetic kidney disease, we treated Mpv17-deficient mice with streptozotocin (STZ) and surprisingly found that they were resistant to diabetes." (PMID 37522959, 2023). "To determine whether MPV17 deficiency would aggravate diabetic kidney disease, we treated male Mpv17 mutant mice aged 8–12 weeks with multiple low-dose STZ (MLDS) for diabetes induction." (PMID 37522959, 2023). "By accident, we found that Mpv17 knockout mice are resistant to STZ-induced diabetes." (PMID 37522959, 2023). "Therefore, MPV17 promotes β-cell apoptosis in diabetes development." (PMID 37522959, 2023). "Together with the observation that β-cell apoptosis was reduced in Mpv17 mutant mice both in STZ and Akita models, these results of correlation study support that MPV17 may promote β-cell apoptosis and its deficiency ameliorates β-cell loss and diabetes." (PMID 37522959, 2023). "MPV17-conferred protection on β-cells occurs in two distinct diabetic mouse models, STZ and Ins2Akita, suggesting that MPV17 may be involved in a common event in STZ- and Ins2Akita-induced diabetes." (PMID 37522959, 2023).
diabetic kidney disease (1 paper, 2023). Progressive kidney disorder caused by vascular damage to the glomerular capillaries, in patients with diabetes mellitus. "We were interested in the role of MPV17 in diabetic kidney disease, and therefore attempted to make Mpv17 mutant mice diabetic by STZ." (PMID 37522959, 2023).
glomerular disease (1 paper, 2023). "Interestingly, the spontaneous glomerular disease of Mpv17 mutant mice, which initially led to death of 90% of the mice at the age of ∼4 months, has become late onset (>1 year of age) in the later breeding, likely due to changes in genetic background." (PMID 37522959, 2023).
gram-positive bacterial infections (1 paper, 2024). Infections caused by bacteria that retain the crystal violet stain (positive) when treated by the gram-staining method. "Similarly, the neural network pays more attention to MPV17-AGPS and MAPK3-SORT1 for the Gram-negative bacterial infected samples and RPS6KA3-JUN for the Gram-positive bacterial infections." (PMID 38827397, 2024).
Hyperglycemia (1 paper, 2023). An increased concentration of glucose in the blood. "This is important given that our study used global knockout of Mpv17 that may affect hepatic or other tissues’ glucose production thereby contributing to the observed attenuation of hyperglycemia in the knockout mice." (PMID 37522959, 2023).
hypermethioninemia (1 paper, 2016). "Some reports have linked hypermethioninemia and hepatic abnormality to mitochondrial depletion syndrome caused by mutations in the MPV17 and DGUOK genes." (PMID 27500280, 2016).
Intellectual disability (1 paper, 2020). "Moreover, Pt2017YS and Pt2017ES with MPV17 deficiency did not develop any complications following LT, whereas Pt2017EB, who had mild intellectual disability before LT, presented with mild headache after LT." (PMID 32703289, 2020).
liver cirrhosis (1 paper, 2022). "Mutations in human MPV17 cause a hepatocerebral form of MDS hallmarked by early-onset severe hypoglycemic crises followed by liver cirrhosis and failure leading to premature death." (PMID 35745859, 2022). "However, when fed a high-fat ketogenic diet (KD), Mpv17 KO mice rapidly develop liver cirrhosis and failure." (PMID 35745859, 2022).
melanoma (1 paper, 2023). A malignant, usually aggressive tumor composed of atypical, neoplastic melanocytes. "We first confirmed the obesogenic effects of zAgRP1 in fish without melanoma by injecting the plasmid into casper (mpv17−/−, mitfa−/−) fish to generate mosaic zAgRP1-overexpressing fish." (PMID 36472402, 2023).
Obesity (1 paper, 2023). Accumulation of substantial excess body fat. "We also do not know the effect of the mpv17 mutation in our casper zebrafish model, which could be relevant for obesity given that it is an inner mitochondrial membrane protein." (PMID 36472402, 2023).
Type 1 diabetes (1 paper, 2023). "It is important to introduce Mpv17 mutation to NOD mice to confirm the role of MPV17 in β-cell apoptosis of Type 1 diabetes." (PMID 37522959, 2023).
Type 2 diabetes (1 paper, 2023). "For Type 2 diabetes, the role of MPV17 in its development is not known because the contribution of β-cell death to Type 2 diabetes development remains a controversial debate topic." (PMID 37522959, 2023).
mitochondrial disease (6 papers, 2016 to 2023). "Interestingly, overexpression of Odc1p was also shown previously to rescue yeast models of mitochondrial diseases caused by defects in the assembly of ATP synthase and by mutations in the MPV17 protein that result in hepatocerebral mitochondrial DNA depletion syndrome." (PMID 28188263, 2017). "Individuals harboring POLG-, TYMP-, or MPV17- deletions or m.8993T>G and m.8993T>C mtDNA mutations, as well as those affected by SURF1-related mitochondrial diseases are at greater risk of developing peripheral neuropathy." (PMID 33383961, 2020).